NF1 (neurofibromin 1)
Diseases named in the same sentence as NF1 in open-access papers (continued):
Sharing a sentence is not in itself a finding about the gene and the disease.
neurofibroma (continued). "MPNSTs are the most aggressive Schwann cell tumors and can arise sporadically or from NF1-mutant plexiform neurofibromas in patients with clinical diagnoses of NF-1." (PMID 38216572, 2024). "Overall, plexiform neurofibroma in peripheral nerves is a rare event in Nf1 tissue-specific knockout mouse models and NPcis mouse models but can be significantly enhanced by cutting the peroneal and tibial nerve of NPcis mice." (PMID 38900740, 2024). "Affecting 1 in 3000 individuals worldwide, approximately 50% of NF1 patients develop plexiform neurofibromas (PNs), a histologically benign heterogeneous nervous sheath tumor arising from Schwann cells that display harbor a biallelic NF1 inactivation." (PMID 39335500, 2024). "In humans, sporadic plexiform neurofibromas carrying a biallelic inactivation of NF1 have been reported in individuals with the rest of the cells being NF1 WT cells." (PMID 38175707, 2024). "MEK inhibitors have been identified as a therapeutic strategy for specific presentations of NF1, such as plexiform neurofibromas." (PMID 38785480, 2024). "An NF1 PV (VAF of 20% and 9% in blood and saliva samples, respectively) was also identified confirming a germline mosaicism for NF1, in accordance with the patient phenotype (large plexiform neurofibroma of the thigh and freckling)." (PMID 39031223, 2024). "In 2020, selumetinib, an MEK inhibitor, was approved in patients with inoperable plexiform neurofibromas affected by neurofibromatosis type 1 (NF1) with hyperactivation of the RAS-MAPK signaling pathway." (PMID 39594917, 2024). "NF1 genetic mutations induce a hyperactive RAS/MEK/ERK pathway, which has led to the approval of selumetinib, a MEK inhibitor, for NF1-associated plexiform neurofibromas." (PMID 39335500, 2024). "As for pharmaceutical treatments, few have been approved for treatment of NF1 oncogenic manifestations, one being selumetinib, targeting plexiform neurofibromas in children." (PMID 38667335, 2024). "Selumetinib, a MEK1/2 inhibitor, has emerged as a promising therapy for inoperable NF1-related plexiform neurofibromas." (PMID 39840093, 2024). "PTEN pathway alterations have been implicated in early NF1-associated tumorigenesis, with marked PTEN reductions found in MPNSTs compared to both neurofibromas and normal nerve tissue." (PMID 38136356, 2023). "A suggested role for metabolic rewiring in the development of NF1-related tumors has been reported, especially in the transformation of neurofibromas into MPNSTs, during which an increased avidity for glucose has been described." (PMID 37627552, 2023). "The recurrent lesion found on multiple generations of the Arsacid Dynasty is possibly a form of neurofibroma secondary to the autosomal dominant, high-penetrance disease NF1." (PMID 37908901, 2023). "As mast cells have been implicated in the growth, vascularization, and spread of neoplastic conditions, investigators studying NF1 have increasingly sought to elucidate the role of mast cells within neurofibromas." (PMID 37817770, 2023). "Molecular analysis is not essential to establish the histological nature of these tumors, although genetic analyses on DNA extracted from PNST (neurofibromas/schwannomas) is required to diagnose mosaic forms of NF1 and SPS." (PMID 37046591, 2023). "Two studies have shown that NF1-/- Schwann cell lineage cells differentiated from patient IPSCs can develop into neurofibromas in immunocompromised mice." (PMID 36854987, 2023). "MPNST often occurs in the context of NF1 as a secondary, malignant transformation of multiple benign neurofibromas throughout the body." (PMID 39516973, 2023). "NF1 minipigs displayed features of NF1 patients such as skin abnormalities, neurofibromas, underwent biallelic inactivation of the NF1 gene, and they also developed OPG." (PMID 38318325, 2023). "Previous studies demonstrated that TGF-β1 induces NF1 patient–derived fibroblasts to form neurofibroma-like phenotypes in vitro, including excessive collagen deposition." (PMID 37140985, 2023).
neurofibroma (continued). "Overall, neurofibromas are more difficult to distinguish from the non-NF1-related lesions using the calculated parameters compared to café-au-lait macules." (PMID 37959212, 2023). "Nonsense suppression in combination with NMD inhibition restored neurofibromin protein expression in primary NF1−/− Schwann cells isolated from minipig neurofibromas." (PMID 37520682, 2023). "Since NF1 is a germline-inherited disease, it makes sense to develop cell-of-origin models for neurofibroma using NF1 patient-derived IPSCs." (PMID 36854987, 2023). "When comparing neurofibromas with non-NF1-related lesions, the mean of p′ minimum 5% values showed the highest accuracy–sensitivity, with 94% sensitivity and 80% specificity." (PMID 37959212, 2023). "Three cohorts of patients were treated with the MEK inhibitor trametinib: cohort 1 (BRAF fusion–positive LGG), cohort 2 (NF1-related optic pathway glioma), and cohort 3 (NF1-related plexiform neurofibroma)." (PMID 37399010, 2023). "Trametinib is also in phase II studies in Australia and New Zealand for NF1-associated OPG and plexiform neurofibromas (ACTRN12620001229965)." (PMID 37124503, 2023). "We report a case of a NF1 patient receiving Selumetinib for plexiform neurofibromas and failing to develop neovascularization after revascularization surgery for concomitant symptomatic MMS." (PMID 36923276, 2023). "Patients with NF-1 and plexiform neurofibromas are 18 times more likely to develop MPNSTs, and 20–30% of MPNSTs occur in patients with NF-1." (PMID 37880773, 2023). "Neurofibromatosis type 1 (NF1) is characterized by nerve tumors called neurofibromas, in which Schwann cells (SCs) show deregulated RAS signaling." (PMID 35311647, 2022). "In the context of NF1, it will be tremendously important to understand the subsequent steps that lead from Nf1 LOH to the creation of neurofibromas." (PMID 36090331, 2022). "The major features of NF1 included the following: NF1 family history in four patients, café-au-lait spots in all, freckling in six, Lisch nodules in three, and neurofibromas in three." (PMID 36405824, 2022). "A series of genetic studies have demonstrated that NF1-homozygous SC lineage cells and haploinsufficiency of NF1 in non-neuronal cells are both required to promote the pathogenesis of neurofibroma." (PMID 36139671, 2022). "Homozygous loss of CDKN2A has also been suggested as an initiating event in the malignant transformation of neurofibromas in NF1 patients." (PMID 34816314, 2022). "Many patients have systemic disorders, predominantly MEN2B, followed by Cowden syndrome and NF1, presenting thyroid and adrenal tumors, trichilemmomas and “cobblestone” tongue lesions, or cutaneous cafe’-au-lait spots and neurofibromas." (PMID 35783634, 2022). "Concerning development of neurofibromas that arise from skin-derived progenitor cells, more than one of these cellular characteristics is fulfilled for NF1." (PMID 34997843, 2022). "Plexiform neurofibroma is a rare kind of NF-1 where the neurofibroma originates from nerve sheath cells or subcutaneous peripheral nerves." (PMID 35308189, 2022). "In a mouse model of NF1, genetic deletion of P2ry14 rescued low cAMP signaling, increased mouse survival, delayed neurofibroma initiation, and improved SC Remak bundles." (PMID 35311647, 2022). "Due to the benign tumor entity and the homogenous ultrasound characteristics of neurofibromas and schwannomas, the disease NF1 can be regarded as a model to explore the potential of SWE for NF2 and PNTs." (PMID 35204451, 2022). "Specifically, neurofibromas, which occur both sporadically and in the setting of NF1, are heterogeneous tumors with small and wavy nuclei, excess “shredded” type collagen, and are immunopositive for neurofilament expression." (PMID 35589737, 2022). "In this regard, NF1+/1809 neurons exhibit elevated RAS activity, similar to neurons with NF1 mutations from patients who develop neurofibromas or optic gliomas." (PMID 35589737, 2022).
neurofibroma (continued). "Pharmacological elevation of cAMP diminished NF1 deficient SCP self-renewal in vitro and reduced SC proliferation in neurofibroma bearing mice in vivo." (PMID 35311647, 2022). "In neurofibromatosis patients, benign neurofibromas develop when the NF1 gene is completely inactivated." (PMID 34997843, 2022). "Because malignant peripheral nerve sheath tumors usually originate from a preexisting plexiform neurofibroma, patients with NF-1, particularly those with plexiform type, should receive regular follow-up to ensure early intervention if necessary." (PMID 35455674, 2022). "Neurofibroma, the most common benign tumor in NF-1, is a peripheral nerve sheath tumor and includes cutaneous, subcutaneous, spinal, and plexiform neurofibromas." (PMID 36010360, 2022). "Some patients with NF-1 develop malignant peripheral nerve sheath tumors that mostly arise from plexiform neurofibromas." (PMID 36010360, 2022). "Plexiform neurofibromas and NF1+ were more prevalent in familial case (28.7% vs 5.7%, p = 0.030; 71.4% vs 30.2%, p = 0.011)." (PMID 35093157, 2022). "A total of three patients with craniofacial NF-1 and histologically confirmed plexiform neurofibromas received preoperative embolization by a radiology team before radical resection of neurofibromas to prevent massive intraoperative blood loss." (PMID 35455674, 2022). "We present data from a cohort of patients with MNF1 with focus on the proportion of neurofibromas, plexiform neurofibromas, MPNST, and other NF1-associated complications." (PMID 33853649, 2021). "Expression of NF1 was also reported in tumor tissues, such as neuroblastoma, neurofibroma, thymoma, and breast cancer." (PMID 34080803, 2021). "PD325901 is a potent MEK inhibitor that has been demonstrated to shrink neurofibromas both in Nf1 mouse models and early stage clinical trials in human NF1 patients." (PMID 34311771, 2021). "Several case series of patients with NF1 have been reported, but there are only a few published reports on neurofibromas of the nipple-areolar complexes." (PMID 34422429, 2021). "We observed that more than half of the NF1-deleted patients had café-au-lait spots, skinfold freckling, Lisch nodules, neurofibromas, neurological abnormalities, and cognitive impairment or learning disabilities." (PMID 34199217, 2021). "A statistically significant association was demonstrated between the presence of HSs and neurofibromas (p = 0.047), and between the presence of HSs and NF1-related retinal microvascular abnormalities (p = 0.017)." (PMID 33757576, 2021). "Many groups took advantage of this system to generate mice with specific manifestations of NF1, using various Cre drivers to generate mice with neurofibromas, OPG, JMML, and other NF1 features." (PMID 33669386, 2021). "While biallelic inactivation is necessary for the development of some clinical findings such as CALMs and neurofibromas, some manifest in haploinsufficiency of NF1." (PMID 33530415, 2021). "Disease penetrance is virtually 100% in adults with NF1, although there is great phenotypic variability in neurofibroma disease burden among patients, even those carrying identical NF1 germline mutations." (PMID 34030682, 2021). "In our atypical NF1 microdeletion patient cohort only the facial dysmorphism, delayed cognitive development, macrocephaly and the presence of subcutaneous neurofibromas were noted." (PMID 34168676, 2021). "The only reported mouse model so far that forms neurofibroma upon Nf1 inactivation and spontaneously leads to MPNST, later on, is the Plp-creERT2; Nf1f/f model." (PMID 34445326, 2021). "NF-1 deletion is characterized with cafe-au-lait spots, neurofibromas and Lisch nodules in the iris." (PMID 34470638, 2021). "Neurofibromas are divided into two subtypes, NF1 and NF2, of which NF1 is caused by mutations in the NF1 gene, is an autosomal dominant disorder that can affect many systems and is the most common neurofibroma." (PMID 33673851, 2021).
neurofibroma (continued). "A statistically significant association was demonstrated between the presence of HSs and neurofibromas, and between the presence of HSs and NF1-related retinal microvascular abnormalities." (PMID 33757576, 2021). "They implanted hiPSC-derived SLCs into mouse sciatic nerve and discovered that NF1-null ones successfully formed authentic neurofibromas in the mouse nerve system, setting up a humanized neurofibroma model." (PMID 34070895, 2021). "Neurofibroma develops as the result of biallelic inactivation in the NF1 tumor suppressor gene in the Schwann cell lineage, leading to an increase in Ras signaling." (PMID 33413690, 2021). "Inactivation of the NF1 gene in the Schwann cell lineage promotes neurofibroma development in a nerve plexus." (PMID 34445326, 2021). "NF1+/ex42del minipigs exhibited manifestations of NF1 syndrome similar to NF1+/R1947X and humans, including CALMs, neurofibromas, tibial narrowing, axillary/inguinal freckling, and shortened stature." (PMID 33669386, 2021). "Currently, it is not well understood how tumor microenvironment impacts neurofibroma progression, however inflammation from NF1 haploinsufficient mast cells is requisite for PNF development." (PMID 33436083, 2021). "Strikingly, overexpression of neuregulin-1 by itself (Nf1 wild type) is sufficient to induce neurofibroma formation followed by MPNST development, although at low frequency." (PMID 34445326, 2021). "During follow-up of NF1, systemic computed tomography (CT) was performed to detect neurological tumors, such as neurofibromas in the brain, spinal cord, and gastrointestinal tract." (PMID 34581917, 2021). "Plexiform neurofibromas (PNF) are benign nerve sheath tumors occurring in neurofibromatosis type 1 (NF‐1)." (PMID 33939292, 2021). "Patients with MNF1 present with plexiform neurofibromas and other NF1-related complications with a frequency requiring that follow-up of MNF1 patients should be in accordance with the standard NF1 guideline in both childhood and adulthood." (PMID 33853649, 2021). "The average NT scores for NF1 were highest for the manifestations plexiform neurofibroma, MPNST and spinal nerve root neurofibroma (ANNEX 3)." (PMID 33903738, 2021). "Plexiform neurofibromas (PNF) and low‐grade gliomas (LGG) are benign tumors associated with Neurofibromatosis type 1 (NF‐1)." (PMID 33939292, 2021). "Higher numbers of subcutaneous and plexiform neurofibromas and higher growth rates of these tumours have been observed in patients with NF1 microdeletions as compared to patients with intragenic pathogenic NF1 variants." (PMID 34535841, 2021). "Approximately 50% of patients with NF1 develop histologically benign plexiform neurofibroma (PN), in which Schwann cells acquire biallelic inactivation of the NF1 gene." (PMID 34464388, 2021). "Individuals with Neurofibromatosis 1 (NF1) are susceptible to both radiation-induced second malignancies and spontaneous progression of plexiform neurofibromas (PNs) to malignant peripheral nerve sheath tumors (MPNSTs)." (PMID 34131650, 2021). "When combined with deletion of Nf1 in the Schwann cell lineage, signatures of senescence are suppressed in resultant neurofibromas, which appear as faster developing, higher grade tumors than produced by deletion of Nf1 alone." (PMID 32353955, 2020). "One out of eight NF1+/ex42del animals developed a neurofibroma which progressed over time, paralleled to imaging characteristics of human neurofibromas, and demonstrated differential maturation on histopathology." (PMID 32193437, 2020). "Internal neurofibromas were detected in all 20 children and adolescents with NF1 microdeletions analysed by whole-body MRI." (PMID 32533297, 2020). "We retrospectively analysed 30 children and adolescents with NF1 microdeletions pertaining to externally visible neurofibromas." (PMID 32533297, 2020).
neurofibroma (continued). "Since MPNSTs develop from internal neurofibromas, a clinical score (NF-1 score) for predicting internal neurofibromas in adults (age > 17 years) was developed and validated to help orient physicians towards imaging studies." (PMID 32014052, 2020). "By 8 months, an NF1+/ex42del boar developed a large diffuse shoulder neurofibroma, visualized on magnetic resonance imaging, which subsequently grew in size and depth as the animal aged up to 20 months." (PMID 32193437, 2020). "Our previous study found that knockdown of HMGA2 inhibits NF1-MPNST growth through MSI2 and that MSI2 expression in NF1-MPNSTs is higher than that in neurofibromas." (PMID 32606289, 2020). "In our previously published Yucatan NF1+/ex42del cohort we demonstrated imaging of neurofibromas in three male NF1 pigs that also presented with CALMs22." (PMID 32193437, 2020). "The one NF1+/ex42del animal that presented with a neurofibroma within 12 months was necropsied at 20 months." (PMID 32193437, 2020). "In this study, we have addressed these issues and investigated the frequency of cutaneous, subcutaneous and plexiform neurofibromas as well as the internal tumour load in children and adolescents with NF1 microdeletions." (PMID 32533297, 2020). "Biallelic inactivation of the tumour-suppressor gene NF1 in glial cells in the skin, along a nerve plexus or in the brain results in the development of benign tumours: cutaneous neurofibroma, plexiform neurofibroma and glioma, respectively." (PMID 32439933, 2020). "For example, NF1-associated MPNSTs typically arise by malignant transformation of an existing plexiform, or nodular or atypical/ANNUBP neurofibroma." (PMID 32252413, 2020). "SOX10 expression is down-regulated in NF1−/− neurofibromas, and it is possible that RUNX1/3 binds to this TF-binding motif in our system to drive neurofibromagenesis." (PMID 31032403, 2019). "ERK phosphorylation caused by loss of NF1 increases RUNX1 activity and contributes to neurofibroma formation." (PMID 31032403, 2019). "Strong evidence indicates that an NF1-/- transformation of SC is key to their hyperproliferation and genesis of all types of NF1 neurofibromas." (PMID 31107888, 2019). "We show that Pmp22 expression decreases significantly in Nf1−/− neurofibroma SCs and increases after Runx1/3 knockout or RUNX1/3-Pmp22–binding site deletion in mouse neurofibroma SCs." (PMID 31032403, 2019). "Conditionally induced Nf1 DI selectively in SC or BCCs of mice also produce neurofibromas within nerve plexuses and nerves as well as pre-cNF-like lesions in the skin, that seem to evolve into overt cNF in the BCCs of Nf1 DI mice." (PMID 31107888, 2019). "All subjects presented CALMs, with freckling in 86% of cases, as well as the most common typical NF1 features including neurofibromas (64.7%), LNs (59.4%), and OPG (16%)." (PMID 31370276, 2019). "Our analyses revealed that robust HMGA2 activation was more prevalent in human NF1-associated MPNSTs (13/16) than in sporadic MPNSTs (16/41), while HMGA2 was inactive in neurofibromas (0/7)." (PMID 31053152, 2019). "Neurofibroma is the main type of NF1, including cutaneous neurofibromas (cNFs), plexiform neurofibromas (pNFs) and malignant peripheral nerve sheath tumours (MPNSTs)." (PMID 31852972, 2019). "Resistance to purinergic agonist is rescued in Nf1 mutant SCs by increasing levels of purinergic stimulation in vitro, and systemic administration of ATP reduced cell proliferation in mouse neurofibroma in vivo." (PMID 30470263, 2018). "We describe a minipig model that exhibits clinical hallmarks of NF1, including café au lait macules, neurofibromas, and optic pathway glioma." (PMID 30302402, 2018). "NF1 minipigs exhibit spontaneous and cell-type-specific LOH, a critical step for both CALM and neurofibroma development in NF1 patients and a hallmark of NF1 that has not been observed in rodent models." (PMID 30302402, 2018).